CD163 (CD163 molecule)
Diseases named in the same sentence as CD163 in open-access papers (continued):
Sharing a sentence is not in itself a finding about the gene and the disease.
astrocytoma (5 papers, 2019 to 2022). "Single CXCL13 and CXCL13/CD163 coexpression predicted poor overall survival in astrocytoma (p = 0.0039 and p = 0.0002, respectively)." (PMID 35570844, 2022). "The Kaplan-Meier survival curve was used to evaluate the relationship between CXCL13, CD163 and patient survival of astrocytoma." (PMID 35570844, 2022). "Multivariate Cox regression analyses manifested CXCL13/CD163 phenotype was a significant independent prognostic indicator of patient outcome in astrocytoma (CXCL13, p = 0.0642; CXCL13/CD163, p = 0.0368)." (PMID 35570844, 2022). "After adjusting for parameters such as gender, age, grade, and recurrence, CXCL13/CD163 coexpression was also regarded as an independent prognostic indicator of patient survival in astrocytoma (HR = 1.682, 95% CI: 1.032–2.740, p = 0.0368)." (PMID 35570844, 2022). "With further analysis of CXCL13 expression and CXCL13/CD163 co-expression, the clinical parameters and prognostic factors were discussed, and their immunomodulatory influences in human astrocytoma were evaluated." (PMID 35570844, 2022). "CXCL13/CD163 coexpression would imply M2c-related aggressive characteristics existing in astrocytoma progression could also provide predictive trends of patient outcomes." (PMID 35570844, 2022). "CXCL13 and CD163 expressions in astrocytoma tissues were displayed by immunohistochemical staining." (PMID 35570844, 2022). "This study is the first to point out that CXCL13 either alone or when co-expressed with M2 pattern CD163 could be a predictive marker of astrocytoma progression and patient outcome." (PMID 35570844, 2022). "CXCL13 and M2 biomarker CD163 were observed by immunohistochemistry in 112 astrocytoma tissues." (PMID 35570844, 2022). "However, significantly more CD163‐positive GAMs were observed in IDH1R132H‐non‐mutant GBMs as compared to IDH1R132H‐non‐mutant astrocytomas of WHO grade II/III." (PMID 30506802, 2019). "The significant increases in CXCL13, CD163, and CXCL13/CD163 immunoreactivity of astrocytoma tissues were found in the apparently aggressive GBM subgroups (CXCL13, p = 0.0002; CD163, p < 0.0001; CXCL13/CD163, p < 0.0001)." (PMID 35570844, 2022). "High level of CXCL13 was detected in 43 (38.39%) astrocytoma and CXCL13/CD163 coexpression was expressed in 33 (29.46%) cases." (PMID 35570844, 2022). "This study further elaborated the clinicopathological significance of CXCL13 co-expressed with CD163, providing a link between CXC chemokine and M2 immunity in human astrocytoma." (PMID 35570844, 2022). "They found that CD163 and CD68, as well as S100A9 rates were elevated in dexamethasone-treated grade I astrocytoma and GBM compared to normal brain tissue and grades II and III tumors." (PMID 33204365, 2020). "Correlation between CXCL13, CD163, CXCL13/CD163 and clinicopathological parameters in astrocytoma." (PMID 35570844, 2022).
colorectal tumor (5 papers, 2019 to 2023). "At the same time, there are studies demonstrating opposite correlations, i.e., poor prognosis of the colorectal tumors showing high amount of CD163+ cells." (PMID 32884895, 2020). "In accordance with the literature, we confirmed that the IF of colorectal tumors was densely infiltrated by macrophages and that, of these, <40% were CD163+ cells." (PMID 31481956, 2019). "Recent work by Yank and colleagues describes an association between higher CD163+/CD68+ ratio at the IF of colorectal tumors and poor prognosis, which is not in accordance with our data." (PMID 31481956, 2019). "First, we created a 7-plex immunofluorescent staining panel to be used on a colorectal tumor tissue (CRC1) consisting of a tumor marker (EPCAM), T-cell markers (CD3, CD4, and CD8), and myeloid markers (CD163, HLA-DR, and XCR1)." (PMID 37731497, 2023). "The CD163 expression level was significantly lower on monocytes from CRC patients compared to healthy donors, suggesting that colorectal tumors influence the phenotype of monocytes." (PMID 32824692, 2020).
depression (5 papers, 2019 to 2026). "A separate analysis of gene expression in microglia from patients with major depressive disorder (MDD) revealed that 81 genes, such as CD163, MKI67, SPP1, CD14, FCGR1A/C, and C1QA/B/C, were found to be downregulated in the microglia of the occipital cortex." (PMID 38607738, 2024).
dermatomyositis (5 papers, 2017 to 2024). Dermatomyositis (DM) is a type of idiopathic inflammatory myopathy characterized by evocative skin lesions and symmetrical proximal muscle weakness. "In individuals with polymyositis and dermatomyositis, serum CD163 levels were positively correlated with disease activity and macrophage density in muscle tissue." (PMID 38651547, 2024). "Studies show that the infiltration of CD163-positive macrophages into alveolar spaces is greater in fatal dermatomyositis-ILD than in survivors and increased serum CD163 levels are associated with a higher mortality rate in DM-ILD subjects." (PMID 38398739, 2024). "In dermatomyositis-associated ILD lung sections, the infiltration of CD163-positive macrophages was severe, and these cells typically expressed gremlin-1." (PMID 33770226, 2021).
dysplasia (5 papers, 2015 to 2025). A usually neoplastic transformation of the cell, associated with altered architectural tissue patterns. "The authors found that the number of CD163+ TAMs significantly increased when comparing high-grade vs. low-grade laryngeal dysplasia and carcinoma-in-situ vs. dysplasia." (PMID 37082492, 2023). "In cervical and oropharyngeal cancer, for example, high infiltration by CD163+ and CD68+ macrophages was correlated with the tumor progression from normal tissue to dysplasia to carcinoma." (PMID 34194435, 2021). "We performed immunohistochemical staining for HLA-I, PD-L1, γH2AX (DNA damage marker), and immune cell markers such as CD8, FOXP3, CD68, and CD163 (in surgically resected specimens from 17 SCRC patients with 12 adjacent normal mucosa (NM) and 9 UC patients with 18 dysplasia/CC tumors." (PMID 37686454, 2023). "Although the etiological roles of CD163+ macrophages and intraepithelial CD4+ T cells in the development of dysplasia are unclear, CD163+ macrophages may contribute to the infiltration of intraepithelial CD4+ T cells." (PMID 26242181, 2015). "Finally, the increased presence of CD163+ MΦ and intraepithelial CD4+ Th1 cells observed in the presence of moderate OED, compared to samples without dysplasia, could be associated with an increased immunogenicity of dysplastic keratinocytes." (PMID 40432828, 2025). "Significant increases in CD163+ macrophages and intraepithelial CD4+ T cells were observed in moderate dysplasia compared to samples without dysplasia." (PMID 26242181, 2015).
endometrial cancer (5 papers, 2019 to 2023). Primary or metastatic malignant neoplasm involving the endometrium (mucous membrane that lines the endometrial cavity). "The levels of infiltrating tumor-associated macrophages (CD68+ and CD163+ cells) positively correlate well with aggressive endometrial cancer as infiltration of such cells progressively increases from normal endometrium to hyperplastic to endometrial cancer." (PMID 31426393, 2019). "Endometrial cancer-draining nodes had higher CD163 values (6.293 ± 6.842 vs. 2.682 ± 3.920, p = 0.0206) and lower CD8 values (10.341 ± 7.614 vs. 25 ± 11.019 p < 0.0001), compared to vulvar cancer-draining nodes." (PMID 36835583, 2023). "Endometrial cancer-draining nodes had higher CD163 values and lower CD8 values, compared to vulvar cancer-draining nodes." (PMID 36835583, 2023). "Based on RNA‐seq and ATAC‐seq analyses, extracellular matrix (ECM) signaling and ECM‐related transcription factors, FOXF2, POU1F1, and RUNX1were identified to potentially be involved in CD163+ macrophage‐induced progestin insensitivity in endometrial cancer patients." (PMID 36373483, 2023). "Infiltrating CD163+ macrophages were correlated with progestin insensitivity in endometrial cancer." (PMID 36373483, 2023). "In addition, we found that low-grade endometrial cancer-draining LNs showed lower S100A/S100B MDSCs and CD163 macrophages than high-grade tumors, with no other significant differences, suggesting a more immunocompetent LN milieu in low-grade tumors." (PMID 36835583, 2023). "Despite also finding lower CD163+ macrophages and higher CD8+ T cells in these nodes, compared to endometrial cancer-draining nodes which would suggest a more immunocompetent microenvironment, the presence of higher PD-L1-positive cells could denote an immunosuppressor activity." (PMID 36835583, 2023).
glaucoma (5 papers, 2019 to 2025). Increased pressure in the eyeball due to obstruction of the outflow of aqueous humor. "In healthy optic nerves, CD163+ macrophages are sparsely distributed along axonal septa, whereas both early- and late-stage glaucoma show increased infiltration of CD163+ macrophages into the nerve bundles." (PMID 41409280, 2025). "Recent work has demonstrated expansion of CD163+ macrophage populations in the optic nerves of human glaucoma patients, however the role of infiltrating immune cells in glaucoma pathogenesis is unknown." (PMID 30670050, 2019). "The authors observed an up-regulation of many proteins in AH from glaucoma patients, which were mostly related to innate immunity, for example higher values of CD14 and CD163, which are monocyte/macrophage markers." (PMID 30967499, 2019). "Recent work has demonstrated that CD163+ macrophage numbers increase in the ONH of human patients with both mild and severe glaucomatous optic neuropathy, and thus, immune-cell infiltration or expansion may be an important part of at least some human glaucomas." (PMID 30670050, 2019).
Hyperglycemia (5 papers, 2017 to 2022). An increased concentration of glucose in the blood. "Apart from IFNγ- and IL-4-mediated regulation of CD163, hyperglycemia elicited an additional suppression of CD163 mRNA in M(IFNγ) compared to normoglycemia." (PMID 35163309, 2022). "There was no functional impairment of endocytosis of Hb-Hp1-1 and Hb-Hp2-2 via CD163 in hyperglycemia." (PMID 35163309, 2022). "To identify the functional consequences of the observed regulation of CD163, we examined the effect of hyperglycemia on the scavenging function of CD163." (PMID 35163309, 2022). "CD163 gene expression was decreased 5.53 times in M(IFNγ) with a further decrease of 1.99 times in hyperglycemia." (PMID 35163309, 2022). "Expression of CD163 is reduced in Hp2-2 carriers and is also further impaired in condition of hyperglycemia." (PMID 32695161, 2020). "Hyperglycemia suppressed CD163 surface expression in M(IFNγ) (1.43 times)." (PMID 35163309, 2022). "Suppression of CD163 expression in M(IFNγ) in hyperglycemia raised the question of whether high-glucose conditions additionally have a direct impact on the scavenging function of CD163." (PMID 35163309, 2022). "In this study, we show for the first time that hyperglycemia interferes with the tolerogenic hemoglobin-haptoglobin scavenging process via CD163 by human primary macrophages, and elevates the production of inflammatory cytokines in response to hemoglobin-haptoglobin complex uptake." (PMID 35163309, 2022). "However, we identified that hyperglycemia enhances the release of inflammatory cytokines in response to scavenging of Hb-Hp complexes via CD163 in M(IFNγ), converting the silent Hb-Hp complex clearing process needed to prevent vascular damage into an inflammatory process." (PMID 35163309, 2022). "In addition, IR and hyperglycemia cause oxidative stress, TACE activation, and CD163 shedding." (PMID 34112902, 2021).
Kawasaki disease (5 papers, 2019 to 2024). A rare inflammatory disease characterized by an acute febrile, systemic, self-limiting, medium-vessel vasculitis primarily affecting children. "Plasma concentrations of ARG1, CCL20, CD163, CORIN, CXCL9, PCSK9 and ADAMTS2 were quantified in MIS-C (n = 22), Kawasaki disease (n = 23), definite bacterial (n = 28) and viral (n = 27) disease and healthy controls (n = 8)." (PMID 38359342, 2024).
kidney damage (5 papers, 2017 to 2022). "Hemozoin-laden CD163+ macrophages were identified in the kidneys and noted with P falciparum-associated kidney damage." (PMID 30937329, 2019). "Previous studies have found that urinary CD163 may be associated with kidney damage." (PMID 33997033, 2021).
Langerhans cell histiocytosis (5 papers, 2016 to 2026). Langerhans cell histiocytosis (LCH) is a systemic disease associated with the proliferation and accumulation (usually in granulomas) of Langerhans cells in various tissues. "Immunohistochemistry further supports its reactive nature, with positivity for CD68 and CD163 indicating macrophage activity, while the absence of langerin and strong CD1a expression helped rule out Langerhans cell histiocytosis." (PMID 41466924, 2025). "ECD cells express the histiocyte marker CD68, CD163, and Factor XIIIa but unlike Langerhans cell histiocytosis do not express CD1a or S100." (PMID 27840753, 2016). "Histopathology confirmed xanthogranulomatous infiltration with foamy histiocytes and Touton giant cells, with immunohistochemistry showing CD68-positive, CD163-positive, CD1a-negative, and S100-negative cells lacking Birbeck granules, consistent with non-Langerhans cell histiocytosis." (PMID 42256999, 2026).
leiomyosarcoma (5 papers, 2014 to 2025). An uncommon, aggressive malignant smooth muscle neoplasm, usually occurring in post-menopausal women. "In leiomyosarcomas, increased tumor-associated macrophage (TAM) infiltration, identified using CD163 and CD68 markers, correlates with worse survival outcomes, particularly in non-gynecologic subtypes, suggesting its utility as a prognostic marker." (PMID 40423041, 2025). "Regarding the macrophage polarization, a higher proportion of M2-like macrophages than M1-like macrophages was observed, particularly in UPS (adjusted mean CD163/CD68 = 20.7) and leiomyosarcoma (adjusted mean CD163/CD68 = 17.4)." (PMID 33802565, 2021). "The 5-year disease-specific survival was <40%, 79%, and 100% in patients with non-gynecologic leiomyosarcomas showing dense, moderate, and sparse CD163+ macrophages, respectively." (PMID 33802565, 2021).
lung diseases (5 papers, 2018 to 2024). "The result of this study suggests that a high concentration of α-defensins could add more risk for bacterial infection-mediated lung diseases by reducing the expression of CD163 and CD206 in AATD individuals." (PMID 38082274, 2023). "Limited research has been conducted on cat CD163 and the infection mechanism of lung disease." (PMID 39459897, 2024). "Because the sequence of CD163 slightly differs in cats, there may be differences when applying the existing M1 and M2 theories to lung disease." (PMID 39459897, 2024). "In addition, the author examines the status of protein structure research on CD163 (one of the markers of anti-inflammatory M2 macrophages) in human and veterinary lung diseases." (PMID 39459897, 2024). "Therefore, our data illustrated that the phenotype of AM taken as a whole, without considering each lung disease separately, was closer to GM-MDM (similar expression of CD163, CD169, CD200R1) than to M-MDM phenotype." (PMID 29562615, 2018).
mantle cell lymphoma (5 papers, 2020 to 2025). Mantle cell lymphoma is a rare form of malignant non-Hodgkin lymphoma affecting B lymphocytes in the lymph nodes in a region called the ``mantle zone''. "In mantle cell lymphoma (MCL), the secretion of CSF-1 polarizes monocytes into specific CD163+ M2-like TAMs (MφMCLs), which promotes the proliferation of lymphoma cells." (PMID 34404434, 2021). "In mantle cell lymphoma (MCL), primary MCL cells transform monocytes into specific CD163+ M2-like macrophages by secreting CSF1 and IL-10." (PMID 32801364, 2020). "Targeting CSF1R caused abrogation of CD163+ TAMs in mantle cell lymphoma (MCL), irrespective of the sensitivity to BTK inhibitors." (PMID 36578079, 2022).
osteoarthritis (5 papers, 2013 to 2025). A noninflammatory degenerative joint disease occurring chiefly in older persons, characterized by degeneration of the articular cartilage, hypertrophy of bone at the margins and changes in the synovial membrane. "The GM-CSF receptor was reported to be overexpressed in CD68+ and CD163+ macrophages from the ST of RA and PsA patients compared with osteoarthritis patients and healthy controls." (PMID 33679701, 2020). "In contrast, significantly increased numbers of CD163+ and TNF-α+ cells were observed in the superior mid-zone of knee cartilage from patients with osteoarthritis (OA) (P<0.05)." (PMID 23326413, 2013). "Mid-zone distribution of CD163+ cells accompanied with increased expression of CD163 and TNF-α were further confirmed in the isolated Col-II+ chondrocytes from the knee cartilage of human patients with osteoarthritis, in contrast to the controls (both P<0.05)." (PMID 23326413, 2013).
preeclampsia (5 papers, 2016 to 2024). Preeclampsia is a hypertensive disorder of pregnancy that is characterized by new-onset hypertension with proteinuria presenting after 20 weeks of gestation, and depending on mild or severe forms may initially present with severe headache, visual disturbances, and hyperreflexia. "The hemoglobin scavenger receptor, CD163, is a macrophage-specific marker and its upregulation was associated with placental dysfunction in preeclampsia and stillbirth." (PMID 31340725, 2019). "Taking into consideration the complexity of the preeclampsia, the PD-L1- and CD163-positive macrophages might play a distinct role in SARS-CoV-2 infection placenta compared with PE." (PMID 39589546, 2024). "In the decidua of patients with preeclampsia, the expression of CD14+, CD163+ and Macrophages was increased, and the number of Macrophages M2 with anti-inflammatory effect was decreased." (PMID 36541903, 2022). "Furthermore, another study elucidates a general change of CD14+/CD163+ or DC-SING/CD163+ (CD14+ and CD163+) Mph in the decidua basalis of women with preterm birth and preeclampsia in comparison with patients without preeclampsia." (PMID 27239344, 2016).
scleroderma (5 papers, 2013 to 2022). Scleroderma is a rare autoimmune connective tissue disorder characterized by abnormal hardening of the skin and, sometimes, other organs. "CD163+ macrophages express chemokines associated with perivascular inflammation, and they recruit inflammatory cells into the perivascular environment in scleroderma." (PMID 35990663, 2022). "Skin CD204 and CD163, both phenotype markers of M2 macrophages, were significantly higher in scleroderma patients than in healthy subjects." (PMID 34784013, 2022). "In this study, we demonstrated that WKYMVm treatment reduced the number of CD68+CD163+ or CD68+Arginase-I+ M2 macrophages in the scleroderma tissues through Fpr2-dependent mechanism." (PMID 31552041, 2019). "The elevation of serum CD163 in scleroderma patients was closely related to disease severity." (PMID 34784013, 2022). "Therefore, we quantified the numbers of M2 macrophages, which include CD68+CD163+ or CD68+Arginase-I+ populations, and M1 macrophages including CD68+NOS2+ and CD68+TLR2+ populations in scleroderma skin." (PMID 31552041, 2019). "The results of our study do not allow us to make firm conclusions about the role of CD163 in the pathogenesis of DU in scleroderma." (PMID 23800379, 2013). "Moreover, WKYMVm treatment did not reduce the numbers of CD68+CD163+ or CD68+Arginase-I+ M2 macrophages in scleroderma skin of Fpr2 KO mice, in contrast to the WKYMVm-induced decrease of M2 macrophage levels in that of wild type mice." (PMID 31552041, 2019).